ENSG00000268163 (novel transcript)
Gene: Protein-coding gene on chromosome 19 (57,437,970 to 57,477,536, reverse strand). Ensembl gene ENSG00000268163.
Genetic constraint (gnomAD): Loss-of-function variants: 10 observed, 17.2 expected, observed/expected ratio (o/e) 0.58, 90% interval 0.36 to 0.99. Missense variants: 141 observed, 150.89 expected, observed/expected ratio (o/e) 0.93, 90% interval 0.81 to 1.08. Synonymous variants: 45 observed, 51.57 expected, observed/expected ratio (o/e) 0.87, 90% interval 0.69 to 1.12.